METTL13 (methyltransferase 13, eEF1A N-terminus and K55)
Diseases named in the same sentence as METTL13 in open-access papers (continued):
Sharing a sentence is not in itself a finding about the gene and the disease.
cancer (34 papers, 2015 to 2026). A tumor composed of atypical neoplastic, often pleomorphic cells that invade other tissues. "As a potential target for cancer therapy, it is necessary to fully explore the role and underlying mechanism of METTL13 in tumorigenesis." (PMID 35925508, 2023). "Although METTL13 has been implicated to be an important oncogene in various cancers, some studies also demonstrated its tumor suppressive function in bladder cancer and clear cell renal cell carcinoma." (PMID 35925508, 2023). "Aberrant expression of METTL13 is linked to cancer, although like METTL11A, the mechanism of oncogenesis appears to be cell type specific." (PMID 36889590, 2023). "Methyltransferase like 13 (METTL13) has been implicated in most human cancers, but its function and mechanism in GC remain elusive." (PMID 35925508, 2023). "Aberrant regulation of METTL13 has been linked to several types of cancer but the precise mechanisms are not yet fully understood." (PMID 34832997, 2021). "METTL13 has 157 mutations annotated in the Catalog of Somatic Mutations In Cancer (COSMIC) database and it has been highlighted as the most mutated METTL protein in comprehensive transcriptomics cancer datasets." (PMID 34832997, 2021). "In summary, aberrant expression of METTL13 has been linked to a wide range of cancers and it has been suggested to function as both oncogene and tumor suppressor." (PMID 34832997, 2021). "In contrast, METTL13 levels have been reported as elevated and linked to unfavorable prognosis for other cancer types." (PMID 34832997, 2021). "Additionally, elevated METTL13 and/or Lys-55 dimethylation levels have been found in various cancers and were in several cases linked to poor prognosis." (PMID 36997089, 2023). "In addition to the numerous links to different types of cancer, METTL13 has also been associated with hearing loss." (PMID 34832997, 2021). "The abundance of METTL13 has been linked to both favorable and poor cancer prognosis." (PMID 34832997, 2021). "Thus, assuming the conservation, targeting METTL13 in cancer therapy could bypass the toxicity associated with targeting essential proteins." (PMID 37347777, 2023). "From a clinical perspective, METTL13 is clearly linked to key cancer hallmarks and recent evidence suggests that combined targeting of METTL13 and key cellular signaling pathways may represent an effective therapeutic strategy in cancer management." (PMID 34832997, 2021). "Previous studies reported that METTL13 promoted various cancers’ development but inhibited the progression of clear cell renal cell carcinoma and bladder cancer." (PMID 39806412, 2025). "Our results uncover a novel role for METTL13 in regulating gene expression in HSPCs, both overlapping with the m6A writer complex, and with unique effects on genes involved in apoptosis and cancer progression." (PMID 41282185, 2025). "Existing studies focus mainly on methylation of eEF1A and changes in translational output, several highlighting the potential oncogenic role of METTL13 in cancer." (PMID 41282185, 2025). "Although METTL13 has been demonstrated to be an important oncogene in various cancers, one study also confirmed its tumor-suppressive function in renal cell carcinoma." (PMID 39711977, 2024). "As a potential target for triggering various cancer progressions, it is necessary to fully explore the potential mechanisms of METTL13 in tumor development." (PMID 39711977, 2024). "METTL13 overexpression markedly promoted epithelial–mesenchymal transition and induced the malignant behaviors of cancer cells." (PMID 39711977, 2024). "By contextualizing METTL13 within the broader landscape of cancer biology and therapeutics, this study serves as an introductory guide to METTL13, aiming to provide readers with a thorough understanding of its role in disease phenotypes." (PMID 39334878, 2024). "METTL13, a member of the N-terminal protein MTase family, has been shown by numerous studies to promote the development of various cancers." (PMID 39711977, 2024).
cancer (continued). "A pivotal role for EEF1A2 emerged in a recent study in gastric cancer revealed that METTL13, which is linked to cancers in humans, works together with EEF1A2 in a loop that causes abnormal levels of the cancer-promoting gene HN1L." (PMID 38172654, 2024). "Currently, the mechanism of METTL13 in cancer is still not clearly understood, and further studies are needed to explore it." (PMID 39128086, 2024). "While METTL13 is generally highly expressed in most human cancer tissues, its expression is weak in normal brain, testicular, and liver tissues." (PMID 39155349, 2024). "Subsequent research has demonstrated that immunogenic METTL13 plays a role in the occurrence of multiple diseases, including various cancers." (PMID 39711977, 2024). "METTL13 and dimethylated K55 on eEF1A are abundant in many human cancers, which correlates with poor patient prognosis." (PMID 37347777, 2023). "Correspondingly, it was found that METTL13 modulates translation rates at specific codons in vivo and is required for efficient growth of Ras-driven cancers." (PMID 36997089, 2023). "Recent studies have strengthened the cancer connection, as proliferation and global protein synthesis are impaired in transformed cells depleted of METTL13." (PMID 37347777, 2023). "METTL13 is expressed ubiquitously and at relatively high levels (compared to other eEF1A-KMTs), especially in cancer cells where METTL13-mediated eEF1A Lys-55 methylation was shown to increase eEF1A GTPase activity and to enhance protein synthesis." (PMID 36997089, 2023). "The authors also convincingly demonstrated that METTL13 depletion sensitized cancer cells to PI3K and mTOR pathway inhibition." (PMID 34832997, 2021). "Methyltransferase like 13 (METTL13) functions as an oncogene in most of human cancers, but its function and mechanism in ccRCC remains unreported." (PMID 33985542, 2021). "Despite the oncogenic role of METTL13 in most of human cancers, not only TCGA database but also GEO dataset showed that METTL13 was underexpressed at transcriptional level in ccRCC tissues." (PMID 33985542, 2021). "Previous studies have reported that METTL13-mediated methylation of eEF1A promotes oncogenesis via increased translation elongation and protein synthesis in cancer cells." (PMID 34381012, 2021). "Future research efforts will likely extend on the current knowledge status, especially how aberrantly regulated METTL13 relates to cancer etiology and progression." (PMID 34832997, 2021). "In bladder cancer, METTL13 has been reported to negatively regulate key cancer hallmarks including proliferation, migration and invasion." (PMID 34832997, 2021). "METTL13 and eEF1AK55me2 levels are upregulated in cancer and negatively correlate with pancreatic and lung cancer patient survival." (PMID 34203525, 2021). "For METTL13 in vivo cancer suppressor’s role comprehensive determination, a subcutaneous xenotransplantation model has been utilized for the consideration of METTL13’s effect on STAD growth expression." (PMID 34476213, 2021). "METTL13 (methyltransferase-like 13) dimethylation of eEF1A on Lys55 (eEF1AK55me2) is utilized by Ras-driven cancers to increase translational output and promote tumorigenesis in vivo." (PMID 34203525, 2021). "FEAT protein is encoded by METTL13 gene (methyltransferase like 13), and it is aberrantly overexpressed in most human cancers but weakly expressed in normal tissues." (PMID 26031775, 2015). "The perturbation gene effect score of METTL13 was considerably lower in cancer cells than in normal cell lines suggesting that targeting this methyltransferase may have limited toxicity in normal tissues." (PMID 39954016, 2025). "Furthermore, METTL13 is identified as a novel oncogene, demonstrating anti-apoptotic properties when cleaved by Caspase-3 in apoptotic cancer cells." (PMID 39155349, 2024). "Moreover, in multiple cancer cell types, METTL13 enhances malignant cellular behaviors such as proliferation, migration, and invasion." (PMID 39155349, 2024).
cancer (continued). "Indeed, it was demonstrated that both eEF2-KMT and the eEF1A MTase METTL13 were required for efficient growth of Ras-driven cancer, and that METTL13 depletion rendered the cancer cells hypersensitive towards other cancer drugs." (PMID 39351878, 2024). "Recently, several studies have explored the role of METTL13 in cancer." (PMID 39128086, 2024). "We speculated that the contradictory roles of METTL13 in cancers may lie in its different modification mechanisms across specific organs." (PMID 39711977, 2024). "METTL13 and eEF1AK55me2 are upregulated in a plethora of human cancers." (PMID 37347777, 2023). "Based on a previous report in live cancer indicating that HN1L could positively regulate METTL13 expression, we tested whether this regulation relationship exists in GC." (PMID 35925508, 2023). "Previous study has indicated that METTL13 is involved in RAS-driven cancer development, we wonder whether depletion of METTL13 in HNSCC is also related to RAS signaling pathway." (PMID 34381012, 2021). "In addition, by using the website UALCAN, we detected that METTL13 expression levels were significantly and negatively correlated to tumor grades and to cancer stages of ccRCC." (PMID 33985542, 2021). "In subsequent studies from the Takahashi lab, METTL13 plasma levels were reported as elevated in several cancer types, and specifically in OvCa, suggesting the protein may have clinical utility as a biomarker." (PMID 34832997, 2021). "Taken together, this indicates that inhibition of METTL13 may represent an effective strategy in combinatorial cancer therapy approaches." (PMID 34832997, 2021). "Therefore, METTL13 has been proposed as a therapeutic target and a clinical biomarker in cancer." (PMID 36997089, 2023). "Therefore, METTL13-eEF1AK55me2 signal pathway is vital for tumors to cope with increased translational demand, and METTL13 inhibition might be an effective way to do targeted intervention for RAS driven cancers." (PMID 35127825, 2021). "METTL13 knockdown inhibited B-ALL driver gene NRAS, and ERBB3, which is frequently overexpressed in cancer." (PMID 41282185, 2025). "Knockdown of METTL3, METTL13 and METTL14 in HSPCs convergently disrupted many immune signaling and survival pathways, while METTL13 knockdown uniquely affected cancer-related pathways." (PMID 41282185, 2025). "Further mechanistic explorations revealed that METTL13 regulated the expression of HN1L (Hematological and neurological expressed 1-like), which is reported to be an oncogene in various cancers." (PMID 35925508, 2023). "We found that METTL13 is necessary and required for proliferation and EMT of HNSCC cancer cells both in vitro and in vivo." (PMID 34381012, 2021). "To investigate the expression pattern of METTL13 in HNSCC, we firstly analyzed its mRNA expression level by qPCR in 67 HNSCC and paired para-carcinoma tissues obtained from Hospital of Stomatology of Sun Yat-sen University." (PMID 34381012, 2021). "METTL13-mediated EEF1A methylation at K55, which resides within its translational (tr)-type GTP-binding domain, has been reported to increase EEF1A GTPase activity in vitro and stimulate protein synthesis in cancer cells." (PMID 41509464, 2026). "The elevated level of METTL13 and the prognosis of cancer patients showed a negative correlation and was a prognostic marker for overall survival in HNSCC patients." (PMID 39289775, 2024). "Previous studies showed that METTL13 is dispensable in non-transformed cells, making it potentially interesting for cancer therapy." (PMID 37347777, 2023). "METTL13 has been evaluated in the context of disease biology, mainly cancer, but the reports are somewhat scattered and do not point in a unified direction." (PMID 34832997, 2021).
cancer (continued). "Furthermore, the ablation of METTL13 reduces proliferation and global protein synthesis in cancer cells, while non-transformed cells appear unaffected." (PMID 37347777, 2023). "Results of METTL13 protein expression obtained from 5 ccRCC cell lines (OS-RC-2, 760-P, ACHN, Caki-1 and 786-O) and a normal renal proximal tubule epithelial cell line (HK-2) showed that METTL13 was significantly underexpressed in most of the cancer cell lines." (PMID 33985542, 2021).
tumor (16 papers, 2015 to 2025). "In accordance with our in vitro results, deficiency of METTL13 in SCC15 cell dramatically suppressed tumor growth when compared with the control in vivo." (PMID 34381012, 2021). "High expression of METTL13 was closely associated with age, tumor size and T classification." (PMID 35925508, 2023). "In vivo, subcutaneous tumor volume increased with METTL13 overexpression and decreased with shMETTL13 treatment and docetaxel (10 mg/kg) administered via intraperitoneal injection twice weekly." (PMID 39806412, 2025). "METTL13-mediated CD44 mRNA decay in CRPC to promote tumor growth and metastasis, thereby promoting docetaxel treatment resistance." (PMID 41194259, 2025). "The results showed that knockdown of METTL13 in T24 cells significantly decreased tumor growth, as evidenced by reduced tumor weight and volume in vivo compared to the control cells." (PMID 39711977, 2024). "For instance, METTL13 from primary tumor cells can enter the circulation by releasing chemical substances that dissolve blood vessel walls." (PMID 39155349, 2024). "Concluding, our results suggest that METL-13-mediated methylation of EEF-1A enhances tumorigenesis in the nematodes, which is reminiscent of the tumor-promoting role of human METTL13." (PMID 37347777, 2023). "In our GC samples, we showed that both mRNA and protein expression of METTL13 were elevated compared to the corresponding non-tumor tissues." (PMID 35925508, 2023). "In a mouse xenograft model, METTL13 overexpression also resulted in larger tumor size and tumor weight." (PMID 35925508, 2023). "In this context, our study indicated the expression of function of a tumor-promoting gene, METTL13, in GC for the first time." (PMID 35925508, 2023). "Consistent with the qRT-PCR result, increased METTL13 protein expression was also observed in GC tissues relative to the matched non-tumor tissues." (PMID 35925508, 2023). "Despite the studies above proving the oncogenicity role of METTL13, an article elucidated its downregulated expression in bladder cancer and its tumor-suppressing functions." (PMID 33985542, 2021). "Downregulation of METTL13 greatly reduced the size and number of tumor spheres when compared with those formed by control cells in both SCC9 and SCC15 cell lines, indicating that their ability to self-renew was impaired." (PMID 34381012, 2021). "Immunohistochemistry results suggested that METTL13 protein expression declined with increase of tumor grade." (PMID 33985542, 2021). "In order to get a more profound understanding of the function of METTL13 in vivo, we obtain the tumor sections." (PMID 34381012, 2021). "METTL13 also functions as a potential inhibitor of apoptosis, for it was found that miR-16 promoted apoptosis of tumor cells by silencing protein synthesis through posttranscriptional regulation." (PMID 34381012, 2021). "Next, hematoxylin and eosin (H&E) staining and METTL13 IHC results verified that METTL13 expression was decreased in sh-METTL13 tumor cells compared to the control." (PMID 34381012, 2021). "Moreover, METTL13 deficiency impaired AML cell proliferation capability in vitro, improved the survival of AML cell line xenograft immune-deficient mice, and reduced tumor infiltration in vivo." (PMID 40382345, 2025). "In vivo experiments showed that METTL13 knockdown inhibited tumor growth and development." (PMID 39711977, 2024). "Statistical analysis revealed an obvious relationship between METTL13 and clinicopathological characteristics, such as age, tumor size and T classification, suggesting that METTL13 could be a potential biomarker for GC." (PMID 35925508, 2023). "Conversely, the overexpression of METTL13 can promote malignant phenotypes of tumor." (PMID 34381012, 2021). "In hepatocellular carcinoma, METTL13 has been implied in mediating tumor growth and metastasis." (PMID 34832997, 2021). "In conclusion, our data revealed the tumor promoter function of METTL13 in HNSCC." (PMID 34381012, 2021).
tumor (continued). "Nevertheless, biomarkers obtained via clinical and translational studies (the role of METTL13/FEAT in infection-driven neoplasia is a good example), as well as ongoing drug trials provide an avenue to examine fluctuations which reflect different stages of the immunopathological process." (PMID 32039196, 2019). "However, tumor stage and METTL13 expression were correlated with the prognosis in HCC patients." (PMID 39128086, 2024). "AGD1 mediates the stemness and apoptosis of PCSCs and promotes docetaxel treatment resistance by enhancing tumor growth and metastasis through USP10/METTL13-mediated CD44 mRNA decay in CRPC." (PMID 39806412, 2025). "Next, we utilized IHC (immunohistochemical staining) to detect METTL13 protein expression in a tissue microarray consisting of 90 tumor samples and 90 non-tumor tissues." (PMID 35925508, 2023). "Moreover, METTL13 knockdown markedly inhibited tumorigenicity of BGC823 cells and decreased tumor weight in nude mice." (PMID 35925508, 2023).
infection (3 papers, 2019 to 2025). The state of being infected such as from the introduction of a foreign agent such as serum, vaccine, antigenic substance or organism. "Instead of narrow promoter-proximal PRO-seq peaks observed in mock infection, promoter peaks in HSV-1 infection often extended into the gene body by a few hundred nucleotides (e.g., ATP5G1) and/or additional downstream peaks were observed as, e.g., for METTL13." (PMID 37093003, 2023).
hematological malignancies (1 paper, 2025). "Collectively, our findings reveal consequences of alterations to the METTL-family in disease development and recognizes an emerging role for METTL13 in hematological malignancies." (PMID 41282185, 2025). "Our findings highlight the effects of METTL13 in malignant transformation, which prompted further analysis to unravel its specific role in hematological diseases." (PMID 41282185, 2025).
METTL13 also shares sentences with these, for which no sentence is quoted: head and neck squamous cell carcinoma (2 papers); T-cell acute lymphoblastic leukemia (2); cardiac hypertrophy (1); chronic lymphocytic leukemia (1); ductal carcinoma in situ of (1); endometrial cancer (1); glioma (1); head and neck cancer (1); liver cirrhosis (1); lymphoid leukemia (1); melanoma (1); nasopharyngeal carcinoma (1); non-Hodgkin lymphoma (1); osteosarcoma (1); pneumonia (1); renal carcinoma (1); squamous cell carcinoma (1).